RNY4P27 (RNY4 pseudogene 27)
Gene: Miscellaneous RNA gene on chromosome 13 (95,336,106 to 95,336,201, reverse strand). Ensembl gene ENSG00000200211.
Homologues: Orthologues: chimpanzee Y_RNA (98% identical), macaque Y_RNA (90% identical). Paralogues in human: RNY4 (90% identical), RNY4P10 (89% identical), RNY4P25 (86% identical), RNY4P7 (86% identical), RNY4P6 (85% identical), Y_RNA (85% identical), RNY4P13 (84% identical), Y_RNA (84% identical), RNY4P14 (83% identical), RNY4P24 (83% identical), RNY4P3 (83% identical), Y_RNA (83% identical), and 86 more.